MIR1225 (microRNA 1225)
Synonyms: hsa-mir-1225; MIRN1225
Gene: MicroRNA gene on chromosome 16 (2,090,195 to 2,090,284, reverse strand). Ensembl gene ENSG00000221656.
Gene Ontology:
Biological process: miRNA-mediated post-transcriptional gene silencing
Homologues: Orthologues: chimpanzee ptr-mir-1225 (100% identical), mouse Gm54763 (93% identical).